CMTM4 (CKLF like MARVEL transmembrane domain containing 4)
Description:
Acts as a backup for CMTM6 to regulate plasma membrane expression of PD-L1/CD274, an immune inhibitory ligand critical for immune tolerance to self and antitumor immunity. May protect PD-L1/CD274 from being polyubiquitinated and targeted for degradation.
Synonyms: CKLFSF4
Tractability: Antibody: UniProt predicts a signal peptide or a membrane-spanning region; the Human Protein Atlas places it where antibodies can reach. PROTAC: its protein half-life has been measured.
Gene: Protein-coding gene on chromosome 16 (66,614,750 to 66,696,743, reverse strand). Ensembl gene ENSG00000183723.
Subcellular location: Membrane
Subcellular location (Human Protein Atlas): Golgi apparatus; Plasma membrane; Vesicles
Gene Ontology:
Molecular function: protein binding
Cellular component: membrane
Genetic constraint (gnomAD): Loss-of-function variants: 8 observed, 12.71 expected, observed/expected ratio (o/e) 0.63, 90% interval 0.37 to 1.14. The upper end of that interval is the gene's LOEUF score, 1.14, which puts it in group 4 of 6, group 1 being the genes least tolerant of losing a copy. Missense variants: 220 observed, 229.85 expected, observed/expected ratio (o/e) 0.96, 90% interval 0.86 to 1.07. Synonymous variants: 104 observed, 94.06 expected, observed/expected ratio (o/e) 1.11, 90% interval 0.94 to 1.3.
Homologues: Orthologues: chimpanzee CMTM4 (100% identical), mouse Cmtm4 (96% identical), rat Cmtm4 (94% identical), pig CMTM4 (94% identical), guinea pig CMTM4 (87% identical), dog CMTM4 (70% identical), tropical clawed frog cmtm4 (68% identical), zebrafish cmtm4 (65% identical), Caenorhabditis elegans F28H1.4 (24% identical), Caenorhabditis elegans F47B3.3 (17% identical). Paralogues in human: CMTM6 (28% identical), CMTM7 (21% identical), PLLP (21% identical), CMTM8 (20% identical), MAL2 (16% identical), CMTM3 (16% identical), MAL (15% identical), PLP2 (15% identical), MARVELD1 (14% identical), CMTM5 (14% identical), CMTM1 (13% identical), CMTM2 (12% identical), and 2 more.
Diseases named in the same sentence as CMTM4 in open-access papers:
CMTM4 is named in the same sentence as 43 diseases in open-access papers, as found by Europe PMC text mining. Sharing a sentence is not in itself a finding about the gene and the disease. The quoted sentences say what the papers report.
clear cell renal cell carcinoma (5 papers, 2015 to 2025). "In clear cell renal cell carcinomas, restoration of CMTM4 expression induces G2/M cell cycle arrest." (PMID 33614606, 2020). "Previous studies in HeLa and clear cell renal cell carcinoma cells imply that CMTM4 functions as a tumor suppressive gene, with expression of CMTM4 leading to cell migration and inhibition of cell proliferation via G2/M phase accumulation." (PMID 30097810, 2019). "CMTM4 has been reported to be frequently downregulated in clear cell renal cell carcinoma where it functions as a tumor suppressor." (PMID 30097810, 2019). "Similar regulation of the cell cycle also occurs in the clear cell renal cell carcinoma cell line 786-O, in which CMTM4 gene expression is lower than that in normal tissue, and restoration of CMTM4 expression upregulates p21 expression at both the protein and mRNA levels." (PMID 32944388, 2020). "CMTM4 and CMTM6, which share 55% amino acid identity, are downregulated in clear cell renal cell carcinoma and lung cancer and act as tumor suppressors." (PMID 40179060, 2025). "Primary clear cell renal cell carcinoma (ccRCC) and the paired adjacent non-tumour tissues were then collected to examine the expression of CMTM4 by western blotting, immunohistochemistry, and quantitative RT-PCR." (PMID 26474560, 2015).
lung carcinoma (4 papers, 2021 to 2025). "In lung carcinoma, loss of CMTM4 significantly reduces tumor growth and impairs NF-κB, mTOR, and PI3K/Akt pathway activation." (PMID 39948411, 2025). "Loss of CMTM4 in lung cancer (LLC), melanoma (B16) or 4T1 was associated with significantly reduced subcutaneous tumor growth in vivo despite a similar growth rate in vitro." (PMID 39948411, 2025). "Instead, CMTM4 can be a prognostic marker for multiple cancer types and a predictive marker for breast and lung cancer patient survival." (PMID 39948411, 2025). "Recent studies have shown that CMTM6 combined with its family member CMTM4 can maintain the stability of PD-L1 and prevent PD-L1 from lysosome hydrolyzation in multiple tumor types, such as melanoma, breast cancer, and lung cancer." (PMID 32770259, 2021). "We confirmed that CMTM4 KD reduced EGFR in LLC lung cancer cell line." (PMID 39948411, 2025).
autoimmune disease (3 papers, 2022 to 2025). A disorder resulting from loss of function or tissue destruction of an organ or multiple organs, arising from humoral or cellular immune responses of the individual to their own tissue constituents. "Collectively, our data identified CMTM4 as an essential component of IL-17R and a potential therapeutic target for treating IL-17-mediated autoimmune diseases." (PMID 36271145, 2022). "Given its role in mediating IL-17A-induced responses, CMTM4 represents a potential new target for the therapy of IL-17A-mediated autoimmune diseases." (PMID 36271145, 2022). "CMTM4 is also identified as a component of IL-17R and mediates autoimmune diseases." (PMID 36782312, 2023). "A strongly decreased protein by C3-LHF1 was CMTM4 (depicted in blue), an essential part of the IL17 receptor responsible for limiting tissue damage in autoimmune diseases, suggesting that the response is more fine-tuned than just detrimental." (PMID 41145914, 2025).
glioma (3 papers, 2022 to 2025). A benign or malignant brain and spinal cord tumor that arises from glial cells (astrocytes, oligodendrocytes, ependymal cells). "Thus, in this study we evaluated the expressions of CMTM6 and CMTM4 in human glioma samples to assess its association with prognosis." (PMID 35983975, 2022). "Interestingly, we found that CMTM6/CMTM4 and PD-L1 co-localized in macrophages are associated with lower OS in glioma, suggesting that CMTM6/CMTM4 may be specific companion diagnostic biomarkers for immunotherapy in gliomas." (PMID 35983975, 2022). "We also confirmed CMTM4 expression in a variety of human carcinoma tissue biopsies, including breast cancer, colon cancer, glioma, melanoma, and prostate cancer." (PMID 39948411, 2025). "CMTM6 mRNA level is significant higher while CMTM4 mRNA level is sharply lower in glioma than in normal tissue." (PMID 35983975, 2022). "CMTM6 mRNA level is increased while CMTM4 mRNA level is decreased as pathological grades increase, which indicates glioma prognosis." (PMID 35983975, 2022). "These bioinformatics data suggest that CMTM6 and CMTM4 likely play an important role in gliomas." (PMID 35983975, 2022). "In summary, we showed that CMTM6/CMTM4 expression is significantly correlated with PD-L1 in gliomas, which corresponds to the role of CMTM6/CMTM4 in the stabilization of PD-L1 in tumor cells." (PMID 35983975, 2022). "Our study confirmed that CMTM4 and CMTM5 are highly expressed in glioma with lower grade and better prognostic subtypes; however, the specific molecular mechanism warrants further investigation." (PMID 35252165, 2022).
hepatocellular carcinoma (3 papers, 2020 to 2022). A malignant tumor that arises from hepatocytes. "Several members, such as CMTM3, CMTM4, CMTM5 and CMTM7, have been documented to exhibit tumor suppressor functions in hepatocellular carcinoma cells." (PMID 33101541, 2020). "In patients with hepatocellular carcinomas, the expression of CMTM4 was reduced compared to matched adjacent non-tumor tissues, and this reduced expression was associated with decreased overall survival rates." (PMID 33614606, 2020). "However, the role of CMTM4 in tumor immunity has not been well clarified, especially in hepatocellular carcinoma (HCC)." (PMID 35986302, 2022).
melanoma (3 papers, 2020 to 2025). A malignant, usually aggressive tumor composed of atypical, neoplastic melanocytes. "Other cancer types, including breast cancer, lung adenocarcinoma, lung squamous cell carcinoma, melanoma, ovarian, pancreatic, and prostate cancers, had higher CMTM4 expression levels, which is consistent with our data." (PMID 39948411, 2025). "Here, we show that CKLF-like MARVEL transmembrane domain-containing member 4 (CMTM4) is highly expressed in multiple human and murine cancer types including Lewis lung carcinoma, triple-negative mammary cancer and melanoma." (PMID 39948411, 2025). "CMTM6 and CMTM4 expression was found in all malignant melanoma (n = 4) and osteosarcoma (n = 4) samples." (PMID 32596272, 2020). "An immunohistochemical analysis using cross-reactive antibodies revealed that canine malignant melanoma and osteosarcoma express CMTM6, CMTM4, and PD-L1 simultaneously." (PMID 32596272, 2020).
pancreatic cancer (3 papers, 2022 to 2024). "The role of CMTM4 is difficult to define, as it exhibits different functions in different tumors, for example, it inhibits the growth of pancreatic cancer cells but its expression level is elevated in type I renal clear cell carcinoma." (PMID 38223763, 2024). "In pancreatic cancer, CMTM4, LAMB3, and IGF2BP2 all promote tumor proliferation, invasion, and metastasis through this activation pathway while inhibiting the cell cycle and apoptosis to play a carcinogenic role." (PMID 35783291, 2022). "CMTM4 can negatively regulate PAK4 to inhibit the PI3K/AKT pathway, which in turn inhibits cell proliferation, and high CMTM4 expression can inhibit pancreatic cancer." (PMID 38223763, 2024).
breast carcinoma (2 papers, 2021 to 2025). "Interestingly, invasive basal and inflammatory breast cancer cell lines exhibited higher CMTM4 expression levels (e.g., SUM190 and BC3) when compared to luminal and mixed breast cancer cell lines, indicating a positive association between CMTM4 expression and tumor aggressiveness/poor outcome." (PMID 39948411, 2025). "Moreover, knockout of CMTM4 in breast cancer cell line 4T1 also confirmed the reduced Akt and NF-κB phosphorylation." (PMID 39948411, 2025). "Similarly, triple-negative basal breast cancer cell lines had higher CMTM4 expression when compared to luminal type cell lines, suggesting that CMTM4 is associated with an aggressive phenotype of cancer." (PMID 39948411, 2025).
head and neck squamous cell carcinoma (2 papers, 2022 to 2024). A squamous cell carcinoma that arises from any of the following anatomic sites: lip and oral cavity, nasal cavity, paranasal sinuses, pharynx, larynx, and salivary glands. "In head and neck squamous cell carcinoma (HNSCC), CMTM4 has a tendency to be overexpressed and unsurprisingly, it can stabilize PD-L1 expression, while CMTM4 also promotes the process of EMT and affects its related molecules." (PMID 38223763, 2024). "CMTM4 expression was found to have a positive correlation with CD8+ and PD-1+ cell density in the stroma of head and neck squamous cell carcinoma." (PMID 35986302, 2022). "The mRNA expression of CMTM4 was found to have a weak positive relationship with PD-L1 in TCGA-LIHC database (rho = 0.116, P = 0.00249), which was consistent with recent studies in head and neck squamous cell carcinoma and undifferentiated pleomorphic sarcoma." (PMID 35986302, 2022).
psoriasis (2 papers, 2022 to 2023). An autoimmune condition characterized by red, well-delineated plaques with silvery scales that are usually on the extensor surfaces and scalp. "Irradiated wild-type mice transplanted with bone marrow grafts from Cmtm4+/+ or Cmtm4−/− littermates showed similar progression of IMQ-induced psoriasis, indicating that CMTM4 had a limited role in the immune cell compartment in this model." (PMID 36271145, 2022). "Accordingly, CMTM4-deficient mice had a severe defect in the recruitment of immune cells following IL-17A administration and were largely resistant to experimental psoriasis, but not to experimental autoimmune encephalomyelitis." (PMID 36271145, 2022). "Therefore, we tested the role of CMTM4 in the imiquimod (IMQ)-induced experimental model of psoriasis, in which the IL-17 signaling in keratinocytes is one of the main drivers of the disease progression." (PMID 36271145, 2022). "Overall, our data indicated that CMTM4 regulates IL-17A signaling in vivo and mediates IMQ-induced psoriasis, while it had only a limited role in MOG-induced EAE." (PMID 36271145, 2022).
and neck cancer (1 paper, 2025). "Adrenal, brain, head, and neck cancer, as well as leukemia patients also showed lower survival rates in the patient group that had higher CMTM4 expression." (PMID 39948411, 2025).
brain cancer (1 paper, 2015). A primary or metastatic malignant neoplasm affecting the brain. "A comprehensive analysis of CMTM4 expression across multiple cancers using bioinformatics indicated that CMTM4 is most significantly downregulated in brain cancers and ccRCC, which implies a tissue-specific function of CMTM4." (PMID 26474560, 2015).
colorectal adenocarcinoma (1 paper, 2020). The most common type of colorectal carcinoma. "In colorectal adenocarcinomas cell lines, over-expression of CMTM4 (in the CMTM4- SW480 cell line) was associated with impeded cell proliferation, reduced migration and reduced levels of AKT phosphorylation." (PMID 33614606, 2020).
Erythema (1 paper, 2022). Redness of the skin, caused by hyperemia of the capillaries in the lower layers of the skin. "Cmtm4−/− mice had substantially milder back skin erythema, scaling and thickening on days 3 and 4 and ear skin thickness on days 2–5 as compared to Cmtm4+/+ mice." (PMID 36271145, 2022).
gastric adenocarcinoma (1 paper, 2021). "In the scRNA-Seq data from primary gastric adenocarcinoma, CMTM6 showed high expression on epithelial cells, T cells, B cells, and macrophages, while CMTM4 was specifically localized on epithelial cells." (PMID 34680324, 2021).
gastric cancer (1 paper, 2022). A primary or metastatic malignant neoplasm involving the stomach. "Interestingly, it was shown that co-expression of CMTM6 and CMTM4 on gastric cancer mesenchymal cells and epithelial cells predicts a poor prognosis and affects the effect of PD-1/PD-L1 immunotherapy." (PMID 36698778, 2022).
lung adenocarcinoma (1 paper, 2025). A carcinoma that arises from the lung and is characterized by the presence of malignant glandular epithelial cells. "Furthermore, in advanced lung adenocarcinoma, CMTM4 expression was significantly higher in stage IV tumor compared to early-stage tumors, suggesting a positive correlation between CMTM4 expression and high-grade tumors." (PMID 39948411, 2025). "Interestingly, the cancer patient tissues at a more advanced stage had higher CMTM4 expression than those at an earlier stage in lung adenocarcinoma." (PMID 39948411, 2025).
ovarian tumors (1 paper, 2025). "In ovarian tumors with high CMTM4 expression, exosomes transfer CMTM4 to macrophages, upregulating ICAM1 and promoting M2 polarization via p65 nuclear translocation." (PMID 40433989, 2025).
renal carcinoma (1 paper, 2015). A carcinoma arising from the epithelium of the renal parenchyma or the renal pelvis. "Using a total of 61 paired ccRCC tissues and adjacent normal tissues, we show that CMTM4 expression is frequently downregulated in renal cancer tissues." (PMID 26474560, 2015). "The protein atlas indicates that the CMTM4 protein is also expressed at lower levels in renal cancer tissues (n = 12, in general, weakly stained or negative) than in normal kidney tissues (n = 2, moderately positive)." (PMID 26474560, 2015).
tumor (26 papers, 2015 to 2026). "CMTM4 was identified as one of the highly expressed genes in multiple tumors and has been implicated in tumor progression." (PMID 39948411, 2025). "In summary, our findings showed a loss of CMTM4 inhibited tumor growth in vivo, and reduced Akt/mTOR signaling and NF-κB activation, which are dependent on the CMTM4 TRAF6 domain." (PMID 39948411, 2025). "Loss of CMTM4 significantly reduced pAKT/mTOR signaling, which is consistent with our findings in murine tumor cell lines." (PMID 39948411, 2025). "Among CMTM family members, CMTM4 is the most conserved member and has been implicated to play a role in tumor progression and modulation of the tumor microenvironment." (PMID 39948411, 2025). "In this study, we showed that CMTM4 regulated tumor growth by modulating tumor-associated inflammation and leukocyte infiltration related to EGFR expression, trafficking, and activation." (PMID 39948411, 2025). "The association between the circCYP24A1/miR-421/CMTM4 pathway and tumor progression was further explored." (PMID 35220395, 2022). "Collectively, the tissue array data demonstrated that CMTM6 expression is associated with poor prognosis irrespective of epithelial or mesenchymal regions, while the association of CMTM4 and prognosis is more restricted to tumor epithelial region." (PMID 34680324, 2021). "Another research analyzed genes consistently overexpressed in 23 solid tumor types, and CMTM4 was identified as one of CD8+ T cell low tumor associated genes." (PMID 33282744, 2020). "However, these phenomena were notably attenuated in ID8/CMTM4 KO tumor‐bearing mice, which was associated with prolonged survival." (PMID 40433989, 2025). "Finally, given the reports about decreased tumor PD-L1 expression with CMTM4 deficiency, and our result that CMTM4 KD tumor was more sensitive to PD-L1 blockade, CMTM4 can also be a predictive biomarker of response to immune checkpoint therapy." (PMID 39948411, 2025). "Indeed, we previously showed LLC and H292 control and CMTM4 KD tumor implanted in immuno-deficient mice grew in a similar rate in vivo, which demonstrated the importance of adaptive immunity, including T cells, in controlling CMTM4 KD tumor growth." (PMID 39948411, 2025). "Although CMTM4 was shown to be highly expressed in various cancer types, its functional roles in tumor progression and establishment of the tumor microenvironment have not been fully investigated." (PMID 39948411, 2025). "Our studies identified CMTM4 as a potential novel target for cancer therapy and controlling tumor inflammation." (PMID 39948411, 2025). "The effects of CMTM4 knockout on tumor cell sensitivity were comparable, with ID8/CMTM4 KO cells showing increased susceptibility to PTX‐induced cell death, further supporting the role of CMTM4 in modulating drug resistance in OC." (PMID 40433989, 2025). "In our cohort, CMTM4 mRNA levels in OC tissues were markedly elevated and analysis revealed a strong positive correlation between high CMTM4 expression and tumor size, Ki67 proliferation index, Tumor‐Node‐Metastasis stage, and histological differentiation." (PMID 40433989, 2025). "Knockout or knockdown of CMTM4 in tumor cells resulted in inhibition of EGFR signaling, mTOR and PI3K/Akt pathways." (PMID 39948411, 2025). "In our study, we found that CMTM4 can modulate the tumor immune microenvironment by promoting EGFR recycling to increase G-CSF and CCL-1 production, which recruit neutrophils and MDSC to induce an immune suppressive tumor microenvironment." (PMID 39948411, 2025). "Sorted MDSCs from CD45.1 tumor-bearing mice were adoptively transferred into control or CMTM4 KD LLC tumor-bearing MaFIA (macrophage Fas-induced apoptosis) mice (CD45.2) that had been depleted of CD115+ cells." (PMID 39948411, 2025). "Recently, CMTM4 has been shown to regulate PD-L1 expression on tumor cells and IL-17 receptor C on stromal cells." (PMID 39948411, 2025).